SNORD115-34 (small nucleolar RNA, C/D box 115-34)
Synonyms: HBII-52-34
Gene: Small nucleolar RNA gene on chromosome 15 (25,232,387 to 25,232,468, forward strand). Ensembl gene ENSG00000199311.
Gene Ontology:
Biological process: RNA processing
Cellular component: nucleolus
Homologues: Orthologues: macaque SNORD115 (100% identical), chimpanzee SNORD115 (96% identical). Paralogues in human: SNORD115-6 (99% identical), SNORD115-11 (98% identical), SNORD115-29 (98% identical), SNORD115-36 (98% identical), SNORD115-42 (98% identical), SNORD115-43 (98% identical), SNORD115-12 (96% identical), SNORD115-15 (96% identical), SNORD115-16 (96% identical), SNORD115-22 (96% identical), SNORD115-26 (96% identical), SNORD115-30 (96% identical), and 37 more.